XRN2 (5'-3' exoribonuclease 2)
Description:
Possesses 5'->3' exoribonuclease activity (By similarity). May promote the termination of transcription by RNA polymerase II. During transcription termination, cleavage at the polyadenylation site liberates a 5' fragment which is subsequently processed to form the mature mRNA and a 3' fragment which remains attached to the elongating polymerase. The processive degradation of this 3' fragment by this protein may promote termination of transcription. Binds to RNA polymerase II (RNAp II) transcription termination R-loops formed by G-rich pause sites.
Tractability: PROTAC: ubiquitination databases record sites on it; its protein half-life has been measured.
Target class: Enzyme; Hydrolase
Gene: Protein-coding gene on chromosome 20 (21,303,304 to 21,389,826, forward strand). Ensembl gene ENSG00000088930.
Subcellular location: Nucleus, nucleolus
Subcellular location (Human Protein Atlas): Nucleoli; Nucleoplasm
Pathways (Reactome):
Metabolism of RNA: Major pathway of rRNA processing in the nucleolus and cytosol; Nuclear RNA decay; mRNA Polyadenylation
Metabolism of proteins: Association of TriC/CCT with target proteins during biosynthesis
Gene Ontology:
Molecular function: 5'-3' exonuclease activity; 5'-3' RNA exonuclease activity; identical protein binding; protein binding; RNA binding; transcription termination site sequence-specific DNA binding; nuclease activity; exonuclease activity; nucleic acid binding
Biological process: spermatogenesis; termination of RNA polymerase II transcription; co-transcriptional mRNA 3'-end processing, cleavage and polyadenylation pathway; RNA catabolic process; RNA metabolic process; RNA processing; rRNA processing; hippocampus development; neuron differentiation; retina development in camera-type eye
Cellular component: membrane; nucleolus; nucleoplasm; nucleus
Genetic constraint (gnomAD): Loss-of-function variants: 40 observed, 126.03 expected, observed/expected ratio (o/e) 0.32, 90% interval 0.25 to 0.41. The upper end of that interval is the gene's LOEUF score, 0.41, which puts it in group 1 of 6, group 1 being the genes least tolerant of losing a copy. Missense variants: 882 observed, 1,154 expected, observed/expected ratio (o/e) 0.76, 90% interval 0.72 to 0.81. Synonymous variants: 334 observed, 371.76 expected, observed/expected ratio (o/e) 0.9, 90% interval 0.82 to 0.98.
Homologues: Orthologues: chimpanzee XRN2 (99% identical), macaque XRN2 (99% identical), rabbit XRN2 (98% identical), dog XRN2 (98% identical), guinea pig XRN2 (98% identical), rat Xrn2 (97% identical), mouse Xrn2 (96% identical), pig XRN2 (93% identical), tropical clawed frog xrn2 (73% identical), zebrafish xrn2 (71% identical), Caenorhabditis elegans xrn-2 (49% identical), Drosophila melanogaster Rat1 (47% identical). Paralogues in human: XRN1 (33% identical).
Diseases named in the same sentence as XRN2 in open-access papers:
XRN2 is named in the same sentence as 30 diseases in open-access papers, as found by Europe PMC text mining. Sharing a sentence is not in itself a finding about the gene and the disease. The quoted sentences say what the papers report.
lung carcinoma (6 papers, 2020 to 2025). "Consistent with concurrent depletion of XRN2 and PARP1 promoting cell death, XRN2-deficient fibroblast and lung cancer cells also demonstrated sensitivity to PARP1 inhibition." (PMID 32859985, 2020). "Importantly, genetic alternations of XRN2, such as mutations, mRNA expression, and copy number variations, are common in a wide range of cancers; XRN2 polymorphisms contribute to an increased risk of spontaneous lung cancer." (PMID 38339346, 2024). "Future studies will focus on elucidating the precise mechanisms by which CREPT influences Xrn2-mediated transcription termination and its implications in lung cancer pathogenesis." (PMID 40860160, 2025). "In fact, it has been shown that XRN2 can mediate the epithelial–mesenchymal transition (EMT) in lung cancer by regulating the maturation of miR-10a." (PMID 35563787, 2022). "In recent years, XRN2 has emerged as a regulator of cancer cell migration in lung cancer and oral carcinoma." (PMID 35563787, 2022). "In lung cancer, it has been suggested that XRN2 regulation of miR-10a is responsible for the migration process." (PMID 35563787, 2022). "Data extracted from these studies are presented here to highlight the relevance of reduced XRN2 expression in breast and lung cancers (respectively)." (PMID 32859985, 2020). "Next, we decided to conduct a “proof of principle” study to explore the applicability of XRN2 depletion as vulnerability against PARP1 inhibition in lung cancer using A549 cell line model." (PMID 32859985, 2020). "Consequently, XRN2 was proposed to be related with poor patient prognosis and induce metastasis in lung cancer through EMT, which was at least partially promoted by miR-10a." (PMID 38689093, 2024). "Regarding its role in miRNA maturation, XRN2 was reported to induce EMT and metastatic behaviors in lung cancer cells by facilitating miR-10a maturation." (PMID 38689093, 2024). "To ensure the broad applicability of PARP inhibitors (PARPi) against XRN2 vulnerabilities, here, we evaluated the effects that other FDA-approved PARPi, Rucaparib, and Olaparib have in XRN2-depleted A549 (lung carcinoma) and MDA-MB-231 (mammary adenocarcinoma) cells." (PMID 38339346, 2024). "Intriguingly, it was experimentally confirmed that XRN2 can degrade only tumor-suppressive miRNAs, not other oncogenic miRNAs, in lung cancer." (PMID 38689093, 2024). "Lastly, we demonstrate that XRN2 alters the transcriptional profile of GBM cells, suggesting that XRN2 can mediate the expression of cellular factors for cell motility and invasion in GBMs similar to the observations in lung cancer." (PMID 35563787, 2022). "XRN2 has been shown to promote the EMT and subsequent metastasis of lung cancer." (PMID 34556138, 2021). "Regarding its role in miRNA degradation, XRN2 can degrade several tumor-suppressive miRNAs, including the let-7 family at the mature miRNA level, without affecting the corresponding pri- or pre-miRNAs in lung cancer, HCC, and glioblastoma cells." (PMID 38689093, 2024).
glioblastoma (5 papers, 2020 to 2024). The most malignant astrocytic tumor (WHO grade IV). "In our current study, we found that a loss of XRN2 reduces cell motility by ~25% in glioblastoma cells when compared to control cells." (PMID 35563787, 2022). "One reason for these observations is that loss of XRN2 disrupts the expression profile of several cellular factors that are important for tumor invasion in glioblastoma multiforme cells." (PMID 35563787, 2022). "A loss of XRN2 decreases cellular speed, displacement, and movement through a matrix of established glioblastoma multiforme cell lines." (PMID 35563787, 2022). "Some tRF-1s may also regulate genes associated with suppression of cellular motility because XRN2 has been shown to be required for cellular invasion in glioblastoma cell lines." (PMID 37146074, 2023). "Additionally, a loss of XRN2 abolishes tumor formation in orthotopic mouse xenograft implanted with G55 glioblastoma multiforme cells." (PMID 35563787, 2022). "We have found that a loss of XRN2 results in increased R-loop formation in glioblastoma cells." (PMID 35563787, 2022). "We found that a loss of XRN2 alters the transcriptional profile of U251 and LN229 glioblastoma cells." (PMID 35563787, 2022). "In our study, we demonstrate that the 5′-3′ exoribonuclease XRN2 is important to the invasive nature of glioblastoma." (PMID 35563787, 2022). "Our current study demonstrates that XRN2 is required for the efficient dissemination of glioblastoma cells." (PMID 35563787, 2022). "XRN2 expression is increased in glioblastoma patient samples as compared to normal brain." (PMID 35563787, 2022). "We provide evidence that XRN2 is important for glioblastoma maintenance in vivo." (PMID 35563787, 2022). "As we have found that XRN2 mediates dissemination of glioblastomas, XRN2′s mechanistic role in this process remains unclear." (PMID 35563787, 2022). "This decrease of Ku70 signal at the 3’ pause region of the β-actin gene was also seen in LN229 or G55 human glioblastoma cells infected with a lentivirus expressing a XRN2 shRNA (LN229-shXRN2 or G55-shXRN2) as compared to LN229 and G55 cells expressing a luciferase shRNA." (PMID 32645903, 2020). "Importantly, XRN2 mRNA and protein levels are elevated in glioblastoma multiforme patient samples." (PMID 35563787, 2022). "While not essential for cell motility, XRN2 is required for efficient glioblastoma cellular movement." (PMID 35563787, 2022).
autism (3 papers, 2021 to 2025). Persistent deficits in social interaction and communication and interaction as well as a markedly restricted repertoire of activity and interest as well as repetitive patterns of behavior. "Additionally, a transcriptome-wide association study (TWAS) found XRN2 to be significantly upregulated in autism, in accord with our findings." (PMID 40373085, 2025). "Additionally, a transcriptome-wide association study (TWAS) found XRN2 to be significantly upregulated in autism, in accordance with our findings." (PMID 37790478, 2023). "XRN2 has been found to play a role in regulating miRNA expression in neurons specifically, and altered miRNA expression regulation has been investigated as a potential mechanism for autism susceptibility." (PMID 37790478, 2023). "It is worth noting that this study also found evidence of SNPs associated with both autism and DNA methylation that were annotated to KIZ and XRN2, two genes that we also found to be significantly associated with ASD." (PMID 37790478, 2023).
triple-negative breast carcinoma (3 papers, 2016 to 2024). An invasive breast carcinoma which is negative for expression of estrogen receptor (ER), progesterone receptor (PR), and human epidermal growth factor receptor 2 (HER2). "Importantly, we then assessed the effect XRN2-depletion has in combination with PARPi in the triple-negative breast cancer cell line, MDA-MB-231." (PMID 38339346, 2024). "Similarly, XRN2 deficient cells, fibroblast or MDA-MB-231 cells, a triple negative breast cancer cell line, were hypersensitive to various genomic insults as illustrated by decreased colony forming ability after exposure to IR, aphidicolin (APH) or hydrogen peroxide (H2O2)." (PMID 27437695, 2016).
breast carcinoma (2 papers, 2016 to 2024). "We found that XRN2-deficient lung and breast cancer cells display sensitivity to two clinically relevant PARP inhibitors, Rucaparib and Olaparib." (PMID 38339346, 2024). "In the current study, we investigated the molecular consequences of XRN2 deficiency in lung and breast cancer cells in conjunction with PARP inhibition via Rucaparib and Olaparib to gain mechanistic insights into the synthetic lethality of XRN2 and PARP1." (PMID 38339346, 2024). "First, we evaluated the sensitivity of XRN2-deficient lung and breast cancer cells against these clinically relevant PARP inhibitors and then delineated the cellular consequences of simultaneous XRN2 deficiency and loss of PARP1 catalytic function." (PMID 38339346, 2024). "Both lung and breast cancer cells depleted in XRN2 using previously validated siRNAs show sensitivity to clinically relevant PARP inhibitors, Rucaparib and Olaparib, over a range of concentrations." (PMID 38339346, 2024). "We also reproduced our results using XRN2 siRNA in MCF-7, an ER+PR+ breast cancer cell line." (PMID 27437695, 2016).
obsessive-compulsive disorder (2 papers, 2023 to 2025). A disorder characterized by the presence of persistent and recurrent irrational thoughts (obsessions), resulting in marked anxiety and repetitive excessive behaviors (compulsions) as a way to try to decrease that anxiety. "In fact, more recent research efforts have focused on ascertaining genetic commonalities between ASD and related disorders such as ADHD, obsessive compulsive disorder (OCD), and Tourette syndrome, of which XRN2 seems to be a shared significant locus." (PMID 37790478, 2023).
schizophrenia (2 papers, 2014 to 2023). A major psychotic disorder characterized by abnormalities in the perception or expression of reality. "In another whole-genome DNA methylation study, six genes (APIS3, C16orf59, KCNK15, LOC146336, MGC16384, and XRN2) were found to be hypermethylated and were identified as good markers of treatment-induced effects in male schizophrenia patients before and after achieving complete remission." (PMID 37772416, 2023).
astrocytoma (1 paper, 2022). "Interestingly, we found that XRN2 mRNA and protein levels were elevated in GBMs, as compared to astrocytoma and oligodendrogliomas." (PMID 35563787, 2022).
atherosclerosis (1 paper, 2014). A disease characterized by the build-up of fatty material and calcium deposition in the arterial wall resulting in partial or complete occlusion of the arterial lumen. "Both SRSF10 and XRN2 were specific master regulators for the advanced atherosclerosis network (P = 0.035, P = 0.040, respectively)." (PMID 24586211, 2014). "Our validation of stage-specific master regulators in the foam cell model of regression suggests that MLL5, SRSF10, and XRN2 will be useful targets for improving atherosclerosis regression after PCL in individuals with mature or even advanced lesions." (PMID 24586211, 2014). "In addition, by inferring PCL-responsive gene networks in early, mature and advanced atherosclerotic lesions, we identified key drivers specific for regression of early (PPARG), mature (MLL5) and advanced (SRSF10/XRN2) atherosclerosis." (PMID 24586211, 2014). "In early lesions, PPARG was identified as a specific master regulator of the PCL-responsive atherosclerosis TF-regulatory network, whereas in mature and advanced lesions, the specific master regulators were MLL5 and SRSF10/XRN2, respectively." (PMID 24586211, 2014).
glioma (1 paper, 2022). A benign or malignant brain and spinal cord tumor that arises from glial cells (astrocytes, oligodendrocytes, ependymal cells). "As RNA:DNA hybrids and miRNAs can act to modulate gene expression, we chose to examine how a loss of XRN2 can influence the global transcriptional profile of gliomas." (PMID 35563787, 2022). "We examined how XRN2 loss affected the migration of glioma cells." (PMID 35563787, 2022). "Using a glioma tissue microarray (product number GL803c) purchased from US Biomax, we examined XRN2 protein expression levels through immunohistochemistry (IHC)." (PMID 35563787, 2022). "We found that XRN2 mRNA levels were elevated in glioma samples as compared to normal brain samples (Berchtold)." (PMID 35563787, 2022). "Thus, to determine if XRN2 is required for invasion, we examined if XRN2 mediates glioma cell invasion through a matrix." (PMID 35563787, 2022).
neuroblastoma (1 paper, 2024). Neuroblastoma (NB) is the most common solid, extracranial childhood tumor. "XRN2 expression was found to be induced by direct binding of MYCN to its promoter region in neuroblastoma cells, and two members of the let-7 family (let-7c and let-7g) were thus significantly upregulated in XRN2-depleted neuroblastoma cells." (PMID 38689093, 2024). "Other research suggested that XRN2 can act as an amplified MYCN-induced mature miRNA-regulatory factor in neuroblastoma by actively degrading a subset of tumor-suppressive miRNAs, further contributing to cancer progression." (PMID 38689093, 2024).
septal defect (1 paper, 2016). "Although neither Nkx2-5+/-nor Xrn2+/- hearts showed a muscular ventricular septal defect (VSD) at postnatal day 0 (P0), we found a VSD in Nkx2-5+/-Xrn2+/-newborn hearts (n = 3 of 7)." (PMID 27331609, 2016).
skin melanoma (1 paper, 2022). "First, we evaluated SAMMSON binding to p32 and XRN2, 2 interaction partners previously identified in skin melanoma, using RIP-qPCR." (PMID 34508176, 2022).
uveal melanoma (1 paper, 2022). A melanoma derived from melanocytes of the uveal tract. "Together with validated p32 and XRN2 interactions, these results suggest a role for SAMMSON in regulating translation and mitochondrial function in uveal melanoma." (PMID 34508176, 2022). "Immunoprecipitation of both p32 and XRN2 in 92.1 and OMM1 cells revealed a 2- and 6-fold enrichment in OMM1 and a 4- and 64-fold enrichment in 92.1 of SAMMSON RNA, respectively, indicating that SAMMSON binding to these factors is conserved in uveal melanoma cells." (PMID 34508176, 2022).
viral infection (1 paper, 2022). "Although its cytoplasmic counterpart, XRN1, has been better studied in the context of viral infection [20,74., 75., 76., 77.], the interplay between XRN2 and viruses remains largely unexplored." (PMID 34509361, 2022).
tumor (8 papers, 2016 to 2025). "Using histological examination, we found that a loss of XRN2 reduced the tumor size visualized through the cross-sectioning of mouse brains." (PMID 35563787, 2022). "Strikingly, a loss of XRN2 resulted in a ~90% reduction in tumor volume when G55 cells were injected into mouse brains." (PMID 35563787, 2022). "Although the basis for this difference remains to be determined, our data support the conclusion that this tumor suppressor, XRN2, functions in the DDR at regions of R-loop-associated transcription termination." (PMID 27437695, 2016). "Consistent with histological data, using magnetic resonance imaging, we found that the tumor volume of two unique XRN2-deficient G55 cells was 5.85 and 2.85 mm3 (G55-shXRN2 (shXRN2-3640) and G55-shXRN2 #2 (shXRN2-3639), respectively), as compared to the 98.8 mm3 volume observed with control cells." (PMID 35563787, 2022). "Overexpression of XRN2 can lead to poorer overall survival rates and increased tumor invasiveness in patients." (PMID 41201287, 2025). "XRN2, as a 5' to 3' ribonuclease, enhances the migratory and invasive abilities of tumor cells when upregulated." (PMID 41201287, 2025). "To further substantiate the effects of circ-XRN2 on in vivo tumor growth, we established stable transfections of HCT116 cells with si-circXRN2 and the corresponding negative control (si-NC)." (PMID 38291092, 2024). "Consequently, XRN2 depletion leads to the accumulation of tumor-suppressive miRNAs, which can functionally target various oncogenes in cancer, and suppresses important cancer properties such as migration and invasion." (PMID 38689093, 2024). "Overall, the evidence indicates that XRN2 can selectively exert its functions to promote cancer progression and enhance malignant phenotypes by either promoting the maturation of oncogenic miRNAs or degrading tumor-suppressive miRNAs in cancer." (PMID 38689093, 2024). "Based on these results, XRN2 seems to play a vital role in tumor development." (PMID 35563787, 2022). "As XRN2 has been shown to mediate epithelial-derived tumor migration, we wanted to know if XRN2 may also drive the motility of non-epithelial cancers, such as GBMs." (PMID 35563787, 2022). "Here, the genes PTBP1, RNF114, XRN2 and ZNRD1 are described as associated with other neoplasms." (PMID 33057419, 2020).